BDNF (brain derived neurotrophic factor)
Diseases named in the same sentence as BDNF in open-access papers (continued):
Sharing a sentence is not in itself a finding about the gene and the disease.
dementia (continued). "Studies have also reported significant changes in peripheral serum brain-derived neurotrophic factor (BDNF) at the late stage of the dementia spectrum." (PMID 39484298, 2023). "A systematic evaluation based on dementia studies showed that probiotic supplements improved memory in patients with dementia, as well as elevated levels of brain-derived neurotrophic factor." (PMID 38287957, 2023). "A similar trend was observed in subjects with severe dementia, in whom BDNF plasma concentrations were increased compared with subjects with normal cognition, but this result was not statistically significant." (PMID 36979505, 2023). "When looking at MMSE scores, BDNF plasma concentrations were significantly higher in subjects with mild and moderate dementia than in subjects with normal cognition." (PMID 36979505, 2023). "Between studies with SAMP8 and those using dementia model mice, common findings were improvement in spatial learning and memory function, and increased levels of DA, 5-HT, and BDNF in serum and brain." (PMID 36749772, 2023). "Presumed cognitive dysfunction blood biomarkers (SAA, Hcy, S100B, BDNF) will be used as predictive factors for the development of MCI or dementia in the study groups." (PMID 37824197, 2023). "In the case of subjects with severe dementia, a similar trend is observed (i.e., higher BDNF levels vs. subjects with MMSE ≥ 25), but the increase in BDNF plasma concentrations is not statistically significant (p = 0.056; Dunn’s post hoc test)." (PMID 36979505, 2023). "It is likely that any BDNF-mediated therapeutic effect of antidepressants would be reduced in dementia due to marked reduction in BDNF levels." (PMID 36621964, 2023). "Significantly higher (H = 19,217.0; p < 0.001) plasma BDNF concentrations are detected in subjects with moderate (p < 0.001; Dunn’s post hoc test) and mild (p = 0.023; Dunn’s post hoc test) dementia compared with subjects with normal cognition." (PMID 36979505, 2023). "A systematic evaluation showed increased levels of brain-derived neurotrophic factor, improved inflammatory profile, and cellular biomarker modulation in patients with dementia taking probiotic Lactobacillus." (PMID 38287957, 2023). "Irisin is a myokine that is secreted from skeletal muscles in response to exercise and enters the central nervous system by crossing the BBB and increasing the expression of BDNF to enhance memory and learning and decreased dementia." (PMID 37600508, 2023). "Our findings indicated that Rn, through its antioxidative, anti-inflammatory, and anti-apoptotic effects, as well as the control of the expression of GFAP, BDNF, and Tau proteins, has a novel neuroprotective impact against scopolamine-induced dementia in rats." (PMID 38323121, 2023). "Further investigation of the effects of BDNF modulation on antidepressant response and mood symptoms in dementia is needed." (PMID 36621964, 2023). "It is therefore important to ensure optimal levels of neurotrophins such as BDNF as a preventive measure for dementia, neuropsychiatric and neurodegenerative diseases." (PMID 36911821, 2023). "Despite the importance of BDNF in T2DM-dementia, the regulation and effect of current anti-diabetic medications on BDNF levels are not well understood and need to be clarified in detail at molecular levels." (PMID 38001940, 2023). "In the present study, we compared BDNF serum levelsin Alzheimer patients with dementia to those in Alzheimer patientswith amnestic mild cognitive impairment and to cognitively healthycontrols." (PMID 37810633, 2023). "BDNF serum concentration is reported to be significantly reduced in patients with severe dementia compared to control subjects." (PMID 35741616, 2022).
dementia (continued). "BDNF levels in platelet-rich plasma significantly decreased, which was correlated with moderate-to-severe stages of dementia." (PMID 35743271, 2022). "Dementia owing to hippocampal long-term potentiation (LTP) degradation appears as a consequence of a decline in BDNF levels or a defect in binding as demonstrated in various researches using BDNF and/or TrkB knockout animals." (PMID 35692417, 2022). "In this study, BDNF levels in dementia patients were higher than those in MCI patients and cognitively normal elderly individuals in the total sample and most subsamples." (PMID 36425322, 2022). "Regular exercise by older adults is believed to not only effectively enhance their fitness but also maintain and improve their cognitive functions and slow the onset of dementia by increasing secretion of neurotrophic factors, such as BDNF and IGF-1." (PMID 35742280, 2022). "These therapeutic drugs enhance recorded low serum BDNF in healthy individuals, and for people who later are likely to developing dementia or AD." (PMID 35625880, 2022). "The study applied Cox models to relate the threat of dementia and AD with levels of BDNF adjusting for probable or potential confounders." (PMID 35625880, 2022). "This stands in contrast to the lower serum BDNF levels observed in patients with advanced dementia stages, possibly due to compromised compensatory capacity." (PMID 34239422, 2021). "Overall, our analyses indicate metabolic regulation of exercise-induced plasma BDNF changes and provide evidence that CTSB is a marker of cognitive changes in late middle-aged adults at risk for dementia." (PMID 34093436, 2021). "To this aim, we chose four candidates that were previously demonstrated to be altered in dementias: BDNF, PGRN, CysC, and GDNF." (PMID 34046409, 2021). "The mean ribose nucleic acid (RNA) expressions of BDNF in 157 HD cases (-0.12 ± 0.20) were significantly lower than that of 157 non-dementia controls (0.16 ± 0.23; P < 0.001)." (PMID 33631722, 2021). "To date, a single study has shown that dementia-free individuals with higher BDNF are less likely to develop dementia and AD." (PMID 33661922, 2021). "ROC curve analysis of BDNF expression as a putative biomarker of dementia showed an AUC of 0.95 (95% CI 0.78–0.99, 100% specificity and 100% sensitivity, p < 0.0001)." (PMID 35008438, 2021). "The beneficial effects of brain-derived neurotrophic factor (BDNF)—a member of the neurotrophin family—on cognitive function or dementia are well established in both rodents and human beings." (PMID 33020545, 2020). "On balance, research to date indicates that the BDNF Met allele is potentially associated with a detrimental influence on the level of cognitive functioning in older adults and may also impart increased risk of progression to dementia through multiple pathways." (PMID 32218234, 2020). "BDNF exerts its essential roles in promoting the hippocampal neurogenesis and rescuing cognitive and motor dysfunctions in a transgenic model of dementia." (PMID 33537297, 2020). "A further element of discussion, also related to the BDNF changes we found, is the relationship between these alterations in neuroinflammatory markers and the development of dementia in DS individuals." (PMID 32280719, 2020). "Molecular mechanisms, implications on interventional trials, and future directions for studies examining BDNF in dementia were discussed." (PMID 30634650, 2019). "Reduced brain-derived neurotrophic factor (BDNF) levels are considered to be a pathogenic event in early AD and even in the earliest, prodromal stages of dementia (e.g., MCI)." (PMID 31591322, 2019). "Many studies have shown that the signaling pathways involving BDNF/pCREB and Akt play crucial roles in the modulation of hippocampal neurogenesis in memory-impaired rodent models and in patients with dementia." (PMID 31331043, 2019). "An age-related reduction in circulating BDNF has been reported both in healthy individuals and in subjects with dementia." (PMID 29330839, 2018).
dementia (continued). "Several studies have shown that the expression of BDNF is impaired in patients with dementia, as well as in amnesia induced animal models." (PMID 30018265, 2018). "Additional factors besides dementia can differentially affect plasma and serum BDNF in AD patients, including proinflammatory cytokines and medications." (PMID 29330839, 2018). "While the exercise-dependent regulation of BDNF is currently undeniable, the role of exercise dependent BDNF as a tool for the improvement of EFs in individuals with dementia is still less clear and seldom discussed." (PMID 28469588, 2017). "The role of XBP1s in dementia is of high significance as it has been shown to exert a protective effect by regulating brain-derived neurotrophic factor (BDNF), which is involved in memory processes." (PMID 28430800, 2017). "Interestingly, DBS of the fornix increases BDNF levels in the hippocampus, an effect which may be linked to the ability of this manipulation to improve memory function in an experimental model of dementia." (PMID 28791332, 2017). "This study has provided direct evidence that BDNF produces a selective but beneficial effect on memory improvement in an AD animal model, which should further establish the use of BDNF as a valid neuroprotective agent for AD-related dementia." (PMID 25849905, 2015). "A recently published study showed that acupuncture at DU20 can up-regulate brain derived neurotrophic factor (BDNF) expression and facilitate the support of BDNF for neurons, thus ameliorate learning and memory in early dementia rats." (PMID 23662137, 2013). "Our results showed a decrease in BDNF serum levels common to the different forms of dementias and an increase in the neutrophin content in patients affected by PD." (PMID 24024214, 2013). "Cerebrolysin (CBL), a mixture of several active peptide fragments and neurotrophic factors including brain-derived neurotrophic factor (BDNF), is currently used in the management of cognitive alterations in patients with dementia." (PMID 23840309, 2013). "Both NGF and BDNF are affected early in the disease and this is thought to initiate a cascade of events which exacerbates pathology and leads to the symptoms of dementia." (PMID 22654716, 2011). "Analysis of BDNF content in the serum of 30 patients at two different stages of AD dementia revealed BDNF values are increased in early stages of AD, while they decrease with the course of the disease, correlating with the severity of dementia." (PMID 22654714, 2011). "In particular, brain-derived neurotrophic factor (BDNF) plays a crucial role in cognition, learning and memory formation by modulating synaptic plasticity and is, therefore, a critical molecule in dementia and neurodegenerative diseases." (PMID 18184369, 2008). "Therefore, natural products with multiple effects represent a useful approach for developing dementia treatments, particularly those targeting neurotrophic factors such as BDNF, which have proven effective in preclinical studies." (PMID 41154559, 2025). "Plasma BDNF protein was especially lower in the severe dementia group (H = 22.2; p < 0.001)." (PMID 41009553, 2025). "Distribution of BDNF Val66Met genotypes (codominant model: AA vs. GA vs. GG genotype carriers, and dominant model A carriers vs. GG homozygotes) was evaluated between individuals with dementia and MCI." (PMID 41009553, 2025). "Fluoxetine may also enhance VEGF, BDNF, and cognition in patients with vascular cognitive impairment and dementia." (PMID 40871684, 2025). "Despite failing to reduce β-amyloid levels, RA may contribute to improving dementia symptoms through reducing hyperglycemia, inducing BDNF, and suppressing the JNK pathway." (PMID 41154559, 2025). "Research indicates that physical activity may modulate brain-derived neurotrophic factor (BDNF), boost neural plasticity, and mitigate age-related brain atrophy, particularly in brain areas linked to dementia such as the hippocampus and frontal temporal lobe." (PMID 41425913, 2025).
dementia (continued). "Moreover, plasma BDNF protein levels were significantly lower in patients with dementia compared to individuals with MCI (U = 12,366.0; p < 0.001)." (PMID 41009553, 2025). "Thus, a decrease in plasma BDNF levels increases the probability of AD onset, but it is possible to delay the progression of dementia by increasing BDNF levels through exercise." (PMID 38337492, 2024). "In the present study, we observed for the first time a significant association between BDNF Met variants and lower volumes in the entorhinal and posterior cingulate cortices among a cohort of elderly normal subjects without evidence of dementia." (PMID 38916728, 2024). "In summary, we examined the effects of Chlorella and PlsEtn from ascidian, which are anticipated to be effective in preventing dementia, both alone and in combination, on the activation of the BDNF–TrkB–CREB signaling pathway, which is known to be decreased in AD patients." (PMID 38257270, 2024). "Although baseline diagnosis was controlled statistically in the statistical modelling, it will be important for future studies with larger sample sizes to clarify the role of BDNF Val66Met on changes in tau and memory across the preclinical, prodromal, and dementia stages of AD." (PMID 38454193, 2024). "In a study involving elderly individuals without dementia, higher serum BDNF levels were associated with a reduced risk of dementia." (PMID 38721229, 2024). "Some studies have focused on how rTMS could influence brain-derived neurotrophic factor (BDNF) levels in dementia." (PMID 40153582, 2024). "The findings imply an adverse impact of the BDNF Met allele on the volumetric integrity of these cortices in the elderly normal subjects without evidence of dementia relative to the naturally occurring Val homozygotes." (PMID 38916728, 2024). "Despite the significant amount of research on BDNF levels in AD and associations with AD pathology, BDNF has not been widely studied in individuals without dementia, particularly investigating the relationship between BDNF levels and cognition." (PMID 36970903, 2023). "We conclude that, with sufficient doses and a proper formulation of probiotic supplementation, serum BDNF can be enhanced along with a reduction in oxidative stress and an increase in antioxidants among dementia patients who have already been clinically diagnosed with AD." (PMID 38201846, 2023). "Interestingly, this vital relationship of serum BDNF with threat of incidental dementia and AD was restricted to women, participants aged >80 years, and those with a college degree." (PMID 35625880, 2022). "BDNF acts as an intermediate among the observed links between the threat of dementia and lifestyle." (PMID 35625880, 2022). "Physical activity (PA) is suggested as a preventive factor for dementia, through substances such as brain-derived neurotrophic factor (BDNF), a neurotrophic and neuroprotective growth factor, which improves brain plasticity and induces neurogenesis and angiogenesis." (PMID 35783131, 2022). "Only weak evidence, that did not survive multiple comparisons, supported the hypothesis that BDNF methylation has the potential to be a biomarker for preclinical or diagnosed dementia." (PMID 35893045, 2022). "The data collected indicates that the role of BDNF is not clearcut in the mechanism of AD but shows that serum BDNF is strongly associated, being more reactive in the case of dementia." (PMID 35625880, 2022). "Nonetheless, since DNA methylation levels, SIRT activity and BDNF expression all significantly decline in patients with dementia or PD, analyzing these three epibiomarkers may be useful in the diagnosis of NDDs." (PMID 35008438, 2021). "In AD patients, hippocampal BDNF mRNA and peripheral BDNF levels were decreased compared to those in the control group, and serum BDNF levels were negatively correlated with future occurrence of dementia and AD, suggesting that BDNF plays a role in protecting the brain from AD." (PMID 34071457, 2021).
dementia (continued). "Clarifying these relationships may further bolster the increased level and compensatory mechanism of plasma BDNF in preclinical dementia." (PMID 34607976, 2021). "Significant changes in the expression of 2,294 genes (1,221 up-regulated and 1,037 down-regulated) were identified in HD versus non-dementia controls; whilst 2,173 DEGs (1,028 up-regulated and 1,145 down-regulated) were determined in BDNF-low versus high group." (PMID 33631722, 2021). "Much likely defensive procedure, essential for the impact of physical activity on dementia danger have been suggested as well as rise in brain derived neurotrophic factor (BDNF), decrease in cardiovascular disease and metabolic syndrome risk, with rise in flow of cerebral blood." (PMID 33407732, 2021). "Since BDNF specifically binds to the TrkB receptor, we hypothesized that the anti-dementia effect of SG-ME may be blocked by ANA-12, a selective TrkB receptor antagonist." (PMID 33281604, 2020). "In a prospective study of 2131 older individuals without dementia, higher serum BDNF level, but not the BDNF Val66Met genotype, was associated with a reduced risk of subsequently developing dementia." (PMID 32218234, 2020). "Therefore, sleep deprivation can lead to BDNF reduction and based on the roles of BDNF and its effects on memory and synapses it can be suggested that through this impairment and reduction, SD and insomnia can result in AD and dementia." (PMID 33023629, 2020). "Therefore, we examined and established the potential role of BDNF in the anti-dementia effect of SG-ME by demonstrating that the effect was lost when an antibody against BDNF was co-administered." (PMID 33281604, 2020). "Because gardening may increase brain-derived neurotrophic factor and platelet derived growth factor, the incidence rate of dementia may decrease." (PMID 32957372, 2020). "Interestingly, the relationship between T2D, BDNF and dementia was reported in one study which demonstrated lower plasma BDNF levels in patient group with both T2D and dementia than in non-diabetic patients with dementia." (PMID 31293498, 2019). "This meta-analysis confirmed the direction of change in serum BDNF levels in dementia." (PMID 30634650, 2019). "This is by far the most interesting prediction, as it could have direct implications for anti-depressive therapies, known to restore cortical BDNF/TrkB signaling and can possibly also counteract dementia." (PMID 31017891, 2019). "Likewise, studies on cerebrospinal fluid (CSF) BDNF levels in AD and other dementias report similar results." (PMID 30403004, 2019). "With these proposed large and clinically well-defined and well-controlled cohorts, the trajectory of BDNF in relation with cognition in AD and dementia could be delineated." (PMID 30634650, 2019). "Moreover, the induction of brain-derived neurotrophic factor (BDNF) production by SA-B in these cells was in line with potential therapy not only to ameliorate the accelerated neuronal cell death in dementia but also their recovery from stem cells." (PMID 29401682, 2018). "Higher serum BDNF levels were suggested to protect against future occurrence of dementia and AD." (PMID 29614679, 2018). "Therefore, improving cholinergic neurotransmission, and regulating the BDNF-CREB pathway by downregulating apoptosis genes is one strategy for inhibiting the etiology of dementia." (PMID 30018265, 2018). "Previously, low BDNF was noted among aging, obese, Alzheimer patients and dementia subjects." (PMID 28316011, 2017). "They concluded that the cerebral output of BDNF, which is negatively related to high plasma glucose levels and decreased BDNF, may be a pathogenetic factor involved not only in dementia, but also in type 2 diabetes." (PMID 24782766, 2014). "BDNF serum concentrations have been reported to correlate with the severity of dementia." (PMID 25371750, 2014).